CDC42BPB (CDC42 binding protein kinase beta)
Description:
Serine/threonine-protein kinase which is an important downstream effector of CDC42 and plays a role in the regulation of cytoskeleton reorganization and cell migration. Regulates actin cytoskeletal reorganization via phosphorylation of PPP1R12C and MYL9/MLC2. In concert with MYO18A and LURAP1, is involved in modulating lamellar actomyosin retrograde flow that is crucial to cell protrusion and migration. Phosphorylates PPP1R12A. In concert with FAM89B/LRAP25 mediates the targeting of LIMK1 to the lamellipodium resulting in its activation and subsequent phosphorylation of CFL1 which is important for lamellipodial F-actin regulation (By similarity).
Synonyms: KIAA1124; MRCKB; CHOCNS
Tractability: Small molecule: a structure with a bound ligand is known; a high-quality ligand is known; it has a high-quality binding pocket; it belongs to a druggable protein family. Antibody: UniProt places it where antibodies can reach, with high confidence; its Gene Ontology location is reachable by antibodies, with medium confidence. PROTAC: ubiquitination databases record sites on it; its protein half-life has been measured; a small molecule that binds it is known.
Target class: Kinase; Protein Kinase; AGC protein kinase DMPK family; AGC protein kinase GEK subfamily; AGC protein kinase group; Enzyme
Gene: Protein-coding gene on chromosome 14 (102,932,380 to 103,057,549, reverse strand). Ensembl gene ENSG00000198752.
Subcellular location: Cytoplasm; Cell membrane; Cell junction; Cell projection, lamellipodium
Pathways (Reactome):
Signal Transduction: CDC42 GTPase cycle; RHOJ GTPase cycle; RHOQ GTPase cycle
Gene Ontology:
Molecular function: protein kinase activity; protein-containing complex binding; ATP binding; magnesium ion binding; protein serine kinase activity; protein serine/threonine kinase activity
Biological process: actomyosin structure organization; cell migration; protein phosphorylation; actin cytoskeleton organization; cytoskeleton organization; establishment or maintenance of cell polarity; signal transduction
Cellular component: actomyosin; anchoring junction; extracellular exosome; plasma membrane; cell leading edge; cell-cell junction; cytoplasm; cytoskeleton; cytosol; lamellipodium
Genetic constraint (gnomAD): Loss-of-function variants: 32 observed, 183.29 expected, observed/expected ratio (o/e) 0.17, 90% interval 0.13 to 0.23. The upper end of that interval is the gene's LOEUF score, 0.23, which puts it in group 1 of 6, group 1 being the genes least tolerant of losing a copy. Missense variants: 1,587 observed, 2,089.5 expected, observed/expected ratio (o/e) 0.76, 90% interval 0.73 to 0.79. Synonymous variants: 883 observed, 845.03 expected, observed/expected ratio (o/e) 1.04, 90% interval 0.99 to 1.11.
Homologues: Orthologues: macaque CDC42BPB (99% identical), dog CDC42BPB (93% identical), rat Cdc42bpb (92% identical), mouse Cdc42bpb (92% identical), pig CDC42BPB (91% identical), chimpanzee CDC42BPB (91% identical), guinea pig CDC42BPB (89% identical), tropical clawed frog cdc42bpb (80% identical), rabbit CDC42BPB (79% identical), zebrafish cdc42bpb (73% identical), Drosophila melanogaster gek (42% identical), Caenorhabditis elegans mrck-1 (37% identical). Paralogues in human: CDC42BPA (62% identical), CDC42BPG (42% identical), CIT (25% identical), ROCK2 (21% identical), ROCK1 (20% identical).
Diseases named in the same sentence as CDC42BPB in open-access papers:
CDC42BPB is named in the same sentence as 29 diseases in open-access papers, as found by Europe PMC text mining. Sharing a sentence is not in itself a finding about the gene and the disease. The quoted sentences say what the papers report.
ganglioglioma (1 paper, 2018). A well differentiated, slow growing neuroepithelial neoplasm composed of neoplastic, mature ganglion cells and neoplastic glial cells. "In the four gangliogliomas that showed tumor progression after subtotal resection, three harbored BRAF p.V600E mutation as the solitary pathogenic alteration without chromosomal copy number aberrations, and the fourth tumor harbored CDC42BPB-BRAF gene fusion." (PMID 29880043, 2018).
holoprosencephaly (1 paper, 2025). Holoprosencephaly (HPE) is a complex brain malformation resulting from incomplete cleavage of the prosencephalon, occurring between the 18th and 28th day of gestation, and affecting both the forebrain and face, which results in neurological manifestations and facial anomalies of variable severity. "Regarding CDC42BPB mutations, cases with cystic changes in the brain have been reported; however, to our knowledge, no cases presenting with holoprosencephaly have been documented." (PMID 40243517, 2025). "Given the expanding phenotypic spectrum of CDC42BPB-related disorders, further studies with larger cohorts are necessary to determine whether holoprosencephaly is a rare manifestation or an incidental finding unrelated to the mutation." (PMID 40243517, 2025).
myocardial infarction (1 paper, 2021). Gross necrosis of the myocardium, as a result of interruption of the blood supply to the area, as in coronary thrombosis. "Moreover, in a replication effort in an independent study three of the genes included in factor 27 were also present in a factor identified to be associated with myocardial infarction (CDC42BPB, MAN2A2 and RPTOR)." (PMID 33836805, 2021). "In this study, we identified 30 MOFA factors and 10 were associated with myocardial infarction; one of them included three genes that were also included in the factor 27 of the FOS cohort: CDC42BPB, MAN2A2, and RPTOR." (PMID 33836805, 2021).
viral infection (1 paper, 2023). "CDC42BPB (ENSG00000259515.1, predicted by LightGBM) could be related to a viral infection that decreases the sense of smell or taste." (PMID 36983953, 2023).
cancer (10 papers, 2009 to 2025). A tumor composed of atypical neoplastic, often pleomorphic cells that invade other tissues. "Furthermore, CDC42BPB, CKAP4, KMT2D, and PBX2 have been shown to be strongly associated with the development of certain cancers." (PMID 40608007, 2025).
neurodevelopmental disorder (2 papers, 2022 to 2024). A behavioral and cognitive disorder with onset during the developmental period that involves impaired or aberrant development of intellectual, motor, or social functions. "Interestingly, one of these target genes, CDC42BPB, has recently been associated with neurodevelopmental disorders including ASD." (PMID 35942939, 2022).
psychiatric disorder (1 paper, 2024). A disorder characterized by behavioral and/or psychological abnormalities, often accompanied by physical symptoms. "Future studies are warranted to investigate the role of CDC42BPB in psychiatric disorders and the degree to which CDC42BPB methylation varies with respect to PTSD onset and treatment response." (PMID 39696436, 2024).
CDC42BPB also shares sentences with these, for which no sentence is quoted: tumor (9 papers); breast carcinoma (4); infection (2); bladder-cancer (1); cerebral palsy (1); cervical tumors (1); Chilton-Okur-Chung neurodevelopmental syndrome (1); colorectal cancer (1); Crohn disease (1); Encephalopathy (1); glioma (1); gynecologic cancers (1); Imerslund-Grasbeck syndrome 2 (1); infectious disease (1); lung squamous cell carcinoma (1); myotonic dystrophy (1); papilloma (1); retinitis pigmentosa (1); skin tumor (1); squamous cell carcinoma (1); stomach cancer (1); triple-negative breast carcinoma (1).